SRGAP2C (SLIT-ROBO Rho GTPase activating protein 2C)
Description:
Human-specific protein that acts as a key modifier of cortical connectivity in the human brain. Acts by inhibiting the functions of ancestral paralog SRGAP2/SRGAP2A, a postsynaptic protein that regulates excitatory and inhibitory synapse maturation and density in cortical pyramidal neurons. SRGAP2C is unstable but is able to heterodimerize with SRGAP2/SRGAP2A, thereby reducing SRGAP2/SRGAP2A levels through proteasome-dependent degradation. Inhibition of SRGAP2/SRGAP2A by SRGAP2C leads to an increase in synaptic density and protracted synaptic maturation of both excitatory and inhibitory synapses. Modifies cortical circuit connectivity by increasing the number of local and long-range cortical inputs received by layer 2/3 pyramidal neurons. Also able to increase the probability of sensory-evoked responses by layer 2/3 pyramidal neurons.
Synonyms: SRGAP2P1
Tractability: PROTAC: ubiquitination databases record sites on it.
Gene: Protein-coding gene on chromosome 1 (121,184,811 to 121,392,874, forward strand). Ensembl gene ENSG00000171943.
Subcellular location (Human Protein Atlas): Cytosol; Basal body; Centrosome
Gene Ontology:
Molecular function: protein heterodimerization activity; protein homodimerization activity; GTPase activator activity
Biological process: cerebral cortex development; excitatory synapse assembly; extension of a leading process involved in cell motility in cerebral cortex radial glia guided migration; inhibitory synapse assembly; negative regulation of dendritic spine development; negative regulation of filopodium assembly; positive regulation of neuron migration; regulation of synapse assembly; negative regulation of cell migration; nervous system development
Cellular component: glutamatergic synapse; dendritic spine
Genetic constraint (gnomAD): Loss-of-function variants: 3 observed, 2.27 expected, observed/expected ratio (o/e) 1.32, 90% interval 0.52 to 1.91. That is too few expected variants to judge how well the gene tolerates losing a copy. Missense variants: 43 observed, 41.98 expected, observed/expected ratio (o/e) 1.02, 90% interval 0.8 to 1.32. Synonymous variants: 14 observed, 15.72 expected, observed/expected ratio (o/e) 0.89, 90% interval 0.59 to 1.39.
Homologues: Orthologues: macaque SRGAP2 (98% identical), mouse Srgap2 (98% identical), rat Srgap2 (98% identical), dog SRGAP2 (90% identical), tropical clawed frog srgap2 (85% identical), zebrafish srgap2 (85% identical), Caenorhabditis elegans srgp-1 (28% identical). Paralogues in human: SRGAP2B (98% identical), SRGAP2 (98% identical), SRGAP1 (77% identical), SRGAP3 (68% identical), ARHGAP4 (44% identical).
Diseases named in the same sentence as SRGAP2C in open-access papers:
SRGAP2C is named in the same sentence as 11 diseases in open-access papers, as found by Europe PMC text mining. Sharing a sentence is not in itself a finding about the gene and the disease. The quoted sentences say what the papers report.
brain malformations (1 paper, 2022). "Bioinformatic analysis suggested that chromosome aberrations potentially disrupt the SRGAP2A genes that are associated with patients with brain malformations and psychiatric diseases, such as epilepsy, while the diploid copy number of the duplicated gene SRGAP2C is highly stable." (PMID 36176941, 2022).
intraepithelial neoplasia (1 paper, 2022). A precancerous neoplastic process that affects the squamous, glandular, or transitional cell epithelium without evidence of invasion. "This provides us with new insights for further exploring the biological mechanisms of lncRNA H19, LINC00895, and lnc-SRGAP2C-16 in the process of chronic non-atrophic gastritis and gastric mucosal low-grade or high-grade intraepithelial neoplasia to GC." (PMID 35571069, 2022).
osteosarcoma (1 paper, 2016). A usually aggressive malignant bone-forming mesenchymal neoplasm, predominantly affecting adolescents and young adults. "Metastatic samples had either 1.8 greater SRGAP2C: SRGAP2 transcript ratio (n = 2) or a two-fold reduction of ENAH compared to primary osteosarcoma samples (n = 5)." (PMID 27966608, 2016). "On average the SRGAP2C: SRGAP2 expression ratio was similar among osteoblasts, primary osteosarcoma samples, and metastatic osteosarcoma samples." (PMID 27966608, 2016). "This study also found that SRGAP2, SRGAP2C, and other genes in the Slit-Robo pathway have altered transcript levels in a subset of mouse and human osteosarcoma, and SRGAP2 protein expression is reduced or absent in half of primary tumor samples." (PMID 27966608, 2016).
tumor (3 papers, 2016 to 2023). "SRGAP2C is a SLIT-ROBO GTPase-activating tumor-suppressing gene located on chromosome 1." (PMID 35629083, 2022). "Hypermethylation of SRGAP2C (Slit-Robo Rho GTPase activating protein 2C) and ZBTB46 (zinc finger and born-to-bind domain containing 46) results in tumorigenesis due to inhibition of their tumour suppressor gene function." (PMID 37233716, 2023). "In this study, an increased SRGAP2C: SRGAP2 transcript ratio or decreased expression of ENAH was found in all juvenile metastatic lesions (n = 7) compared to osteoblasts and primary tumor samples (n = 5)." (PMID 27966608, 2016).
cancer (2 papers, 2022 to 2023). A tumor composed of atypical neoplastic, often pleomorphic cells that invade other tissues. "Five genes were implicated in the development of other cancer types: SRGAP2C, MAP3K1, FGFR2, LSP1, and FMNL3." (PMID 36703164, 2023). "Hypermethylation and reduction in TSG function of SRGAP2C (Slit-Robo Rho GTPase-activating protein 2C) and ZBTB46 (zinc finger and born-to-bind domain containing 46) were associated with tumorigenesis and cancer metastasis." (PMID 35629083, 2022). "Additionally, the genes SRGAP2C, LSP1, and FMNL3 have been implicated in the etiology of other types of cancer." (PMID 36703164, 2023). "The promoter-region DMR on SRGAP2C showed significant hypermethylation between all three groups, with the lowest at 14% proportional change between the obese and non-obese cancer group, and it revealed a marginal interaction with age in the GR model." (PMID 35629083, 2022).
SRGAP2C also shares sentences with these, for which no sentence is quoted: epilepsy (1 paper); infection (1); Obesity (1); oligospermia (1); psychiatric diseases (1); teratospermia (1).